B9D1 (B9 domain containing 1)
Description:
Component of the tectonic-like complex, a complex localized at the transition zone of primary cilia and acting as a barrier that prevents diffusion of transmembrane proteins between the cilia and plasma membranes. Required for ciliogenesis and sonic hedgehog/SHH signaling (By similarity).
Synonyms: MKSR1; B9; EPPB9; MKS9; MKSR-1; JBTS27
Tractability: PROTAC: ubiquitination databases record sites on it.
Gene: Protein-coding gene on chromosome 17 (19,334,308 to 19,378,193, reverse strand). Ensembl gene ENSG00000108641.
Subcellular location: Cytoplasm, cytoskeleton, cilium basal body; Cytoplasm, cytoskeleton, cilium axoneme
Subcellular location (Human Protein Atlas): Acrosome; Equatorial segment; Mid piece; Nucleoplasm; Basal body; Cytosol; End piece; Principal piece; Vesicles
Pathways (Reactome):
Organelle biogenesis and maintenance: Anchoring of the basal body to the plasma membrane
Gene Ontology:
Molecular function: protein binding; hedgehog receptor activity
Biological process: cilium assembly; protein localization to ciliary transition zone; smoothened signaling pathway
Cellular component: centrosome; ciliary basal body; ciliary transition zone; cytosol; MKS complex; axoneme; cilium; membrane
Genetic constraint (gnomAD): Loss-of-function variants: 17 observed, 24.92 expected, observed/expected ratio (o/e) 0.68, 90% interval 0.47 to 1.02. The upper end of that interval is the gene's LOEUF score, 1.02, which puts it in group 4 of 6, group 1 being the genes least tolerant of losing a copy. Missense variants: 200 observed, 211.26 expected, observed/expected ratio (o/e) 0.95, 90% interval 0.84 to 1.06. Synonymous variants: 82 observed, 79.28 expected, observed/expected ratio (o/e) 1.03, 90% interval 0.86 to 1.24.
Gene-disease validity (ClinGen):
ClinGen rates the evidence that B9D1 causes each of these diseases.
ciliopathy (autosomal recessive): Definitive. A genetic disorder of the cellular cilia or the cilia anchoring structures, the basal bodies, or of ciliary function.
Homologues: Orthologues: chimpanzee B9D1 (100% identical), mouse B9d1 (95% identical), guinea pig B9D1 (94% identical), pig B9D1 (92% identical), rabbit B9D1 (90% identical), rat B9d1 (77% identical), dog B9D1 (77% identical), zebrafish b9d1 (76% identical), tropical clawed frog b9d1 (71% identical), Drosophila melanogaster B9d1 (31% identical), Caenorhabditis elegans mksr-1 (25% identical). Paralogues in human: MKS1 (29% identical), B9D2 (22% identical).
Diseases named in the same sentence as B9D1 in open-access papers:
B9D1 is named in the same sentence as 10 diseases in open-access papers, as found by Europe PMC text mining. Sharing a sentence is not in itself a finding about the gene and the disease. The quoted sentences say what the papers report.
ciliopathy (9 papers, 2013 to 2025). "B9D1 is important for ciliogenesis and has been implicated in ciliopathies including Meckel syndrome, characterized by renal cystic dysplasia and CNS defects, and Joubert syndrome, characterized by cerebellar and brainstem malformation." (PMID 37968596, 2023). "Notably, mutations in B9D1 gene are implicated in Meckel syndrome, a severe ciliopathy that is perinatally lethal due to polydactyly, kidney disease, liver fibrosis, and CNS defects." (PMID 40924492, 2025). "The B9D1 gene was first associated with MKS in 2011, after the conducting of Next-Generation Sequencing (NGS) targeting 31 ciliopathy-associated genes in 12 MKS-affected families." (PMID 40565534, 2025). "This underscores the importance of postmortem evaluations in future cases to better understand potential genotype-phenotype correlations and the full spectrum of organ involvement in B9D1-related ciliopathies." (PMID 40933483, 2025). "Our comprehensive review of the literature highlights the emerging role of B9D1 in the pathogenesis of ciliopathies in the clinical and scientific landscape over the past fifteen years." (PMID 40565534, 2025). "In addition to this, 661W cells express several syndromic ciliopathy disease genes which are not expressed at all in hTERT-RPE1 cells, including B9d1, B9d2, Evc2, Pkd1, and Tmem138." (PMID 31024622, 2019).
Joubert syndrome (6 papers, 2014 to 2025). Joubert syndrome (JS) is characterized by congenital malformation of the brainstem and agenesis or hypoplasia of the cerebellar vermis leading to an abnormal respiratory pattern, nystagmus, hypotonia, ataxia, and delay in achieving motor milestones. "The sucrose shock-specific program also included two Meckel/Joubert syndrome genes (B9D1 in cluster 2 and NPHP3 in cluster 4)." (PMID 35924891, 2022). "Accordingly, a patient with Joubert syndrome (JBTS), carrying a heterozygous mutation in the CC2D2A gene and two variants in the B9D1 gene, was described by Kroes and colleagues." (PMID 40565534, 2025).
Meckel syndrome (5 papers, 2014 to 2025). "Here, we report a recurrent pedigree with biallelic pathogenic variants of B9D1 and a clinical and radiological phenotype consistent with Meckel syndrome." (PMID 40933483, 2025). "Here we describe four patients with mild Joubert phenotypes who carry pathogenic mutations in either MKS1 or B9D1, two genes previously implicated only in Meckel syndrome." (PMID 24886560, 2014).
Ataxia (1 paper, 2025). Ataxia refers to impaired coordination of voluntary muscle movement. "The first case was a 9-year-old boy presenting with hypotonia, ataxia, developmental delay, intellectual disability, oculomotor abnormalities (OMAs), nystagmus, MTS, and dysmorphisms, with the homozygous c.467G>A; p.(Arg156Gln) variant in B9D1." (PMID 40565534, 2025).
attention deficit-hyperactivity disorder (1 paper, 2020). A disorder characterized by a marked pattern of inattention and/or hyperactivity-impulsivity that is inconsistent with developmental level and clearly interferes with functioning in at least two settings (e.g. at home and at school). "GIT1, a novel interactor of B9D1 is associated with attention deficit hyperactivity disorder and MME, a novel interactor of SPAG1with Alzheimer’s disease." (PMID 32973177, 2020).
dilated cardiomyopathy (1 paper, 2024). Cardiomyopathy which is characterized by dilation and contractile dysfunction of the left and right ventricles. "The B9D1 gene hypomethylation was found in the heart tissue and blood of dilated cardiomyopathy, and mutations in B9D1 result in disturbed heart development from disrupted cliogenesis." (PMID 39596076, 2024).
schizophrenia (1 paper, 2022). A major psychotic disorder characterized by abnormalities in the perception or expression of reality. "Interestingly, other variants were found in hmsLRI-E connected to genes that had not been previously associated with schizophrenia (KIZ, CDKAP2, EPN2, MAPK7, B9D1)." (PMID 35887306, 2022).
B9D1 also shares sentences with these, for which no sentence is quoted: kidney disease (1 paper); liver fibrosis (1); renal cystic dysplasia (1).